NEAT1 (nuclear paraspeckle assembly transcript 1)
Diseases named in the same sentence as NEAT1 in open-access papers (continued):
Sharing a sentence is not in itself a finding about the gene and the disease.
Sepsis (79 papers, 2017 to 2025). Sepsis is defined as life-threatening organ dysfunction caused by a dysregulated host response to infection. "Non-coding RNAs are similarly affected – exosomal NEAT1 (a lncRNA) is increased and linked to sepsis-associated encephalopathy, while circRNA_104484/104670 show diagnostic potential." (PMID 40787977, 2025). "A recent study revealed that the expression of NEAT1 was significantly increased while the expression of miR-495-3p was decreased in burn-associated sepsis and that the expression of these two molecules was associated with the clinical features of patients." (PMID 40821971, 2025). "Circulating lncRNA NEAT1 is associated with an unfavorable prognosis and increased risk in sepsis patients." (PMID 39067063, 2025). "Taken together, these data suggest that ATF3/ILF3/NEAT1 axis is implicated in M2 polarization in CLP-induced sepsis model." (PMID 38395749, 2024). "More importantly, NEAT1 is upregulated in patients with sepsis, and associated with elevated inflammation, increased sepsis risk and poor survival." (PMID 38395749, 2024). "NEAT1, located on chromosome 11q13.1, is associated with a variety of inflammatory diseases, including sepsis." (PMID 38395749, 2024). "The affluence of NEAT1 and scarcity of miR-125a also increase the risk, severity, and mortality rate of sepsis." (PMID 36675533, 2023). "Nuclear Enriched Abundant Transcript 1 (NEAT1) is another lncRNA that was found to be implicated in sepsis-induced myocardial injury in a recent study." (PMID 36012630, 2022). "The lncRNA NEAT1 was associated with disease severity, higher mortality risk, and unfavorable prognosis in sepsis patients." (PMID 34041287, 2021). "For instance, the expression of lncRNA NEAT1 was up-regulated in patient serum and associated with severity of sepsis." (PMID 34055659, 2021). "In our research, we explore the function and potential underlying mechanism of NEAT1 in sepsis-induced inflammatory response." (PMID 33710444, 2021). "NEAT1 showed a good predictive value for increased sepsis risk.NEAT1 expression was positively associated with disease severity, CRP, PCT, TNF-α, and IL-1β, 28-day deaths." (PMID 34956235, 2021). "The results of this study show that high expression of NEAT1 is associated with severity of sepsis and knockdown of NEAT1 attenuates LPS-induced inflammatory response in macrophages, possibly by acting as a ceRNA of miR-17-5p to regulate TLR4." (PMID 32099901, 2020). "The function and underlying regulatory mechanism of NEAT1 in sepsis were further investigated by subsequent experiments." (PMID 32414769, 2020). "Recent evidence has confirmed that circulating NEAT1 is positively related to the risk, severity, and unfavorable prognosis in patients with sepsis." (PMID 32089649, 2020). "Correlation analysis showed that the expression of Irak2 was positively associated with NEAT1 in sepsis tissues." (PMID 32414769, 2020). "These protective functions are lost when increased NEAT1 levels sponge miR-204, activating NF-κB signaling and leading to sepsis associated organ failure in sepsis-induced AKI patients." (PMID 30717168, 2019). "This study aims to evaluate the diagnostic value of nuclear-enriched abundant transcript 1 (NEAT1) expression in peripheral blood mononuclear cells (PBMCs) for the early diagnosis of sepsis." (PMID 29463949, 2017). "Furthermore, NEAT1 promotes ferroptosis in Parkinson's disease, Streptococcus pneumoniae-induced alveolar epithelial cell injury, and sepsis-associated encephalopathy by modulating different molecular axes." (PMID 41268533, 2025). "Additionally, the higher expression of NEAT1 is associated with a good prognosis in sepsis patients." (PMID 40362651, 2025). "Likewise, high lncRNA NEAT1 expression showed close correlation with increased disease risk, enhanced severity, and higher 28-day mortality in sepsis." (PMID 34483898, 2021). "However, the underlying mechanism of NEAT1 in sepsis-induced inflammatory response remains to be revealed." (PMID 33710444, 2021).
Sepsis (continued). "NEAT1 in circulating blood is associated with increased disease risk, ascending severity of the disease, poor prognosis, and rising expression of inflammatory factors in sepsis patients." (PMID 34666672, 2021). "Moreover, emerging evidence suggests that in sepsis patients, NEAT1 is correlated with increasing risk, severity and poor prognosis." (PMID 32099901, 2020). "NEAT1 expression was enhanced in patient serum and associated with severity of sepsis." (PMID 32099901, 2020). "From these results, it could be concluded that NEAT1 might be a vital immunoregulatory factor and have a diagnostic value in sepsis." (PMID 32414769, 2020). "In our study, NEAT1 expression was enhanced in sepsis patients and was associated with severity of patients; suggesting that NEAT1 might be a promoter of sepsis development, as previously shown." (PMID 32099901, 2020). "Moreover, they showed that NEAT1 could be an essential diagnostic marker and therapeutic target for brain injury induced by sepsis." (PMID 35038133, 2022). "The nuclear-enriched abundant transcript 1 (NEAT1) is one of the most upregulated lncRNAs in experimental sepsis." (PMID 40868190, 2025). "Exosomal NEAT1 is consistently elevated in sepsis patients, particularly those with encephalopathy, correlating with disease severity and brain injury markers." (PMID 40787977, 2025). "In a mouse model of sepsis, the knockdown of Neat1 accelerates T lymphocyte viability and reduces apoptosis." (PMID 40362651, 2025). "For instance, lncRNA NEAT1 increases the inflammatory response in sepsis-induced liver injury by regulating the Let-7a/TLR4 (Toll-like receptor 4) signaling pathway." (PMID 39067063, 2025). "A previous study revealed that ATF3 triggers M2 macrophage polarization to protect against inflammatory injury during sepsis via the ILF3/NEAT1 axis." (PMID 41181154, 2025). "Several studies have reported that the silencing of NEAT1 ameliorates sepsis-induced apoptosis, inflammation, and inhibition of proliferation, as well as mitigates kidney injury." (PMID 40657645, 2025). "lncRNA NEAT1 plays a crucial role in sepsis-induced severe injury by modulating miR-204 and the NF-κB signaling pathway." (PMID 39067063, 2025). "Other studies also indicated that the expression of NEAT1 and miR-495-3p changed in sepsis and that NEAT1 exhibited great potential for sepsis diagnosis and treatment, considering its modification of miR-495-3p in inflammatory cell models." (PMID 40821971, 2025). "This study identified four hub genes (CLEC4D, GPR84, S100A12, and HK3) with significant prognostic value in sepsis and predicted a ceRNA network (NEAT1-hsa-miR-495-3p-ELF1) regulating their expression." (PMID 40821971, 2025). "Several studies have demonstrated that NEAT1 is significantly upregulated in sepsis-induced AKI in both cellular and mouse models." (PMID 40657645, 2025). "The molecular mechanism by which NEAT1 contributes to M2 polarization in sepsis need in-depth investigation in the future study." (PMID 38395749, 2024). "In vitro functional experiments and in vivo studies in cecal ligation and puncture (CLP)-induced sepsis model revealed that ATF3 facilitated M2 polarization in sepsis via ILF3/NEAT1 axis." (PMID 38395749, 2024). "To investigate the biological roles of ATF3/ILF3/NEAT1 axis, we first examined the expression of these molecules in sepsis." (PMID 38395749, 2024). "For instance, NEAT1 is negatively correlated with miR-124 in sepsis, and NEAT1/miR-124 axis correlates with different clinical parameters of sepsis." (PMID 38395749, 2024). "Mechanistic studies have demonstrated that NEAT1 and miRNA work in concert to regulate inflammation in sepsis." (PMID 38395749, 2024). "ATF3 triggers M2 macrophage polarization to protect against the inflammatory injury of sepsis through ILF3/NEAT1 axis." (PMID 38395749, 2024).
Sepsis (continued). "A number of studies have illustrated that NEAT1 regulates inflammatory response in sepsis, thereby modulating septic complications, such as sepsis-induced myocardial, kidney or lung injury." (PMID 38395749, 2024). "In summary, we reported that ATF3 triggered M2 macrophage polarization to protect against sepsis-induced lung injury through ILF3/NEAT1 axis." (PMID 38395749, 2024). "In the current study, we reported that ATF3 protected against sepsis-induced ALI by promoting M2 polarization via ILF3/NEAT1 axis, shedding light on the targeted therapeutic strategies for sepsis." (PMID 38395749, 2024). "NEAT1 boosts the expression of pro-inflammatory cytokines in sepsis patients, whereas it provides a poor prognosis in sepsis." (PMID 36675533, 2023). "Upregulated NEAT1 but downregulated miR-22-3p was observed in patients with sepsis and in LPS-induced HK-2 cells." (PMID 37215112, 2023). "Increasing evidences demonstrate that lncRNAs are essential regulators of inflammatory response and potential biomarkers of sepsis, including NEAT1, HOTAIR, UCA1 and HULC." (PMID 36817490, 2023). "As most previous experiments have been performed using cell lines, additional studies involving animal models or primary macrophages isolated from patients with sepsis are warranted to confirm the role of NEAT1 in sepsis progression." (PMID 37509544, 2023). "Liu and his colleagues recently demonstrated that lncRNA NEAT1 promoted apoptosis and inflammation in LPS‐induced H9c2 cells by targeting miR‐590‐3p, providing new strategies for the treatment of sepsis." (PMID 36817490, 2023). "Previous studies have found a considerable increase in NEAT1 levels in serum of patients with sepsis and septic mouse models." (PMID 37509544, 2023). "In Sepsis, NEAT1 inhibits the activation of NF-κB signaling pathway by up-regulating miR-144-3p, thus alleviating LPS-induced myocardial injury." (PMID 38114929, 2023). "Meanwhile, the expression levels of NEAT1 were also obviously higher in the patients with sepsis than in healthy controls." (PMID 35464083, 2022). "Numerous scholars have also intensively studied the function of long noncoding RNA nuclear-enriched abundant transcript 1 (NEAT1) in sepsis-induced AKI." (PMID 35350698, 2022). "Not only brain injury, NEAT1 also plays an important role in sepsis-induced liver injury by promoting inflammatory responses via the ceRNA regulatory axis." (PMID 35038133, 2022). "The present study provided a clue for SAE of sepsis-induced ferroptosis through axis NEAT1/miR-9-5p/TFRC and GOT1." (PMID 35038133, 2022). "One study had found that the expression of lncRNA NEAT1 in the blood of patients with sepsis is significantly increased." (PMID 35038133, 2022). "The expression of serum exosomal NEAT1 was upregulated in a CLP rat model, possibly promoting ferroptosis by regulating the miR-9-5p/TFRC and GOT1 axes, thereby exacerbating sepsis-associated encephalopathy." (PMID 36579343, 2022). "LncRNA nuclear-enriched abundant transcript 1 (NEAT1) seems to also be involved in sepsis progression." (PMID 35741168, 2022). "Combined together, we demonstrated that the expression of NEAT1 was elevated in rats with sepsis-induced ferroptosis." (PMID 35038133, 2022). "We investigate the ceRNA axis NEAT1/miR-9-5p/TFRC/GOT1 on sepsis-induced ferroptosis for the first time in the present study." (PMID 35038133, 2022). "We further explored the downstream cascade of NEAT1/miR-31-5p axis involved in sepsis-induced inflammatory response, and found miR-31-5p target gene, POU2F1." (PMID 33710444, 2021). "Collectedly, these results demonstrated that knockdown of NEAT1 exerted an inhibition effect on inflammatory response and apoptosis of LPS-induced sepsis in RAW264.7 cells." (PMID 33710444, 2021). "Similar to MALAT1, NEAT1 can promote the progression of sepsis through promoting cell apoptosis, enhancing immune response, and decreasing cellular activity." (PMID 34630395, 2021).
Sepsis (continued). "Through sequestering these miRNAs, NEAT1 can affect several molecular pathways in the course of sepsis." (PMID 34956235, 2021). "All in all, these data demonstrated that NEAT1 regulated the progression of sepsis via sponging miR-31-5p." (PMID 33710444, 2021). "Subsequent studies in sepsis patients further demonstrated that the direct interaction of NEAT1 with the target miR-125a increased apoptosis of lung epithelial cells, which ultimately led to poor prognosis of ARDS." (PMID 34630395, 2021). "High expression of NEAT1 in peripheral blood mononuclear cells (PBMCs) can be considered as an additive marker for the diagnosis of sepsis, while another study confirmed that monocyte-enriched NEAT1 was suppressed in post-MI patients." (PMID 34041287, 2021). "Although these studies suggest that NEAT1 is closely related to sepsis-induced inflammatory response, the specific mechanism of NEAT1 in sepsis progression is still worth investigating." (PMID 33710444, 2021). "On the other hand, lncRNA NEAT1 knockdown in CLP-induced sepsis mice alleviated brain injury by reducing apoptosis and downregulating NF-κB pathway." (PMID 34055659, 2021). "LncRNA nuclear-enriched abundant transcript 1 (NEAT1) involved in sepsis progression has been reported." (PMID 33710444, 2021). "While MALAT1 and NEAT1 promoted sepsis-induced inflammation in organ injury, TUG1 exhibited protective effects by inhibiting apoptosis, promoting cell proliferation, and downregulating immune response in sepsis." (PMID 34630395, 2021). "NEAT1 expression was significantly increased in patients with sepsis-induced acute kidney injury and correlated positively with severity of sepsis." (PMID 34514170, 2021). "In summary, all these findings demonstrated that NEAT1 promoted inflammatory response in sepsis via the miR-31-5p/POU2F1 axis, and it provided a novel therapeutic target for sepsis." (PMID 33710444, 2021). "In a word, this study indicates that NEAT1 inhibits the LPS-induced progression of sepsis in RAW264.7 cells by modulating miR-31-5p/POU2F1 axis, suggesting that NEAT1 will be the potential therapeutic target for sepsis." (PMID 33710444, 2021). "LncRNA such as NEAT1, HOTAIR, and MALAT1 have been identified as being significantly associated with the development of sepsis." (PMID 34870560, 2021). "In a sepsis-induced liver injury model NEAT1 was also observed to compete against Let-7a to release TLR4, promoting subsequent inflammatory response." (PMID 34630395, 2021). "NEAT1 is another lncRNA whose participation in the pathophysiology of sepsis has been vastly investigated." (PMID 34956235, 2021). "Downregulation of NEAT1 has restricted immune response in mouse model of sepsis and induced T cell apoptosis through modulating miR-125/MCEMP1 axis." (PMID 34804042, 2021). "and demonstrated that circulating lncRNA NEAT1/miR-124 axis had a better potency for diagnosis and prognosis of sepsis." (PMID 34055659, 2021). "Here we first provided the regulatory network of NEAT1/miR-17-5p/TLR4, revealing novel theoretical basis for application of NEAT1 in sepsis treatment." (PMID 32099901, 2020). "NEAT1 and Irak2 were upregulated in sepsis tissues and LPS-induced RAW 264.7 and HL-1 cells, opposite to the expression of miR-370-3p." (PMID 32414769, 2020). "Nuclear enriched abundant transcript 1 (NEAT1) is another lncRNA found to be involved in sepsis-induced myocardial damage in a recent study." (PMID 33396834, 2020). "Thereby down-regulating NEAT1 through siRNA attenuated LPS-induced inflammatory response in macrophages, indicating the potential therapeutic effect of NEAT1 in sepsis." (PMID 32099901, 2020). "High levels of the long noncoding RNA nuclear paraspeckle assembly transcript 1 (NEAT1) have been positively correlated with increased severity and unfavorable prognoses in patients with sepsis." (PMID 32089649, 2020).
Sepsis (continued). "In the pathogenesis of sepsis, increased lncRNA NEAT1 binds to Let-7a competitively, and TLR4 is released from Let-7a, which is activated and stimulates downstream signals, leading to severe inflammatory responses." (PMID 31664225, 2020). "Previous work showed that NEAT1 was highly expressed in sepsis-induced acute kidney injury patients and aggravated LPS-induced injury." (PMID 32099901, 2020). "To explore how NEAT1 affects sepsis-evoked ALI, we constructed a mouse model of ALI via LPS injection in vivo." (PMID 32089649, 2020). "Though these studies showed that NEAT1 was closely associated with sepsis-induced injury, the regulatory mechanism of NEAT1 in sepsis progression is still worth studying." (PMID 32414769, 2020). "In conclusion, the study demonstrated that NEAT1 was upregulated, while miR-22-3p wasdownregulated in patients with sepsis and in LPS-induced HK-2 cells." (PMID 33335994, 2020). "Similar to our results, miR-144 has been previously reported as a DEM in sepsis patients as compared to healthy controls, which acts by regulating the NF-kB signaling pathway and NEAT1 in the sepsis model." (PMID 33182754, 2020). "In our research, NEAT1 was clearly upregulated in sepsis tissues and LPS-induced RAW 264.7 and HL-1 cells." (PMID 32414769, 2020). "Nuclear-enriched abundant transcript 1 (NEAT1), a member of the long non-coding RNAs (lncRNAs), was reported to be involved in the regulation of sepsis progression." (PMID 32414769, 2020). "Further research indicated that downregulation of miR-370-3p or upregulation of Irak2 rescued NEAT1 silencing-mediated inhibitory effect on sepsis progression." (PMID 32414769, 2020). "Further research demonstrated that overexpression of Irak2 transposed the repressive impact of NEAT1 silencing on sepsis progression." (PMID 32414769, 2020). "Knockdown of NEAT1 hampered sepsis progression by downregulating Irak2 via interacting with miR-370-3p in LPS-induced RAW 264.7 and HL-1 cells." (PMID 32414769, 2020). "Long noncoding RNA nuclear enriched abundant transcript 1 (NEAT1) has been reported to be involved in sepsis development." (PMID 32099901, 2020). "To investigate the function of NEAT1 in sepsis progression, we first checked the level of NEAT1 in LPS-induced RAW 264.7 and HL-1 cells infected with small interfering (si)-NEAT1 and matched controls." (PMID 32414769, 2020). "Taken together, these results suggest that upregulation of Irak2 transposed the NEAT1 silencing-mediated suppressive effect onto sepsis progression." (PMID 32414769, 2020). "In this research, the expression level of NEAT1 in sepsis tissues and LPS-induced RAW 264.7 and HL-1 cells was checked." (PMID 32414769, 2020). "Together, these results demonstrated that NEAT1 and miR-370-3p played opposite roles in sepsis progression and NEAT1-regulated sepsis progression via interacting with miR-370-3p." (PMID 32414769, 2020). "As reported, NEAT1 promoted inflammatory response in sepsis-induced liver injury, and NEAT1 also facilitated hepatic lipid accumulation and exacerbated NAFLD." (PMID 33228663, 2020). "To study the relationship between Irak2 and NEAT1 in sepsis progression, we first transfected LPS-induced RAW 264.7 and HL-1 cells using pcDNA-Irak2 or pc-DNA-control." (PMID 32414769, 2020). "Consistent withprevious studies, we verified that inhibition of NEAT1 alleviated sepsis-stimulated AKIby inhibiting the intrinsic apoptosis, autophagy, and inflammatory response." (PMID 33335994, 2020). "The results revealed that NEAT1 expression wasdramatically increased, while the miR-22-3p expression was significantly decreased in patientswith sepsis compared with healthy controls." (PMID 33335994, 2020). "In conclusion, our research demonstrated that NEAT1 silencing obstructed sepsis progression by decreasing the expression of Irak2 by sponging miR-370-3p." (PMID 32414769, 2020).